INAVA (innate immunity activator)
Description:
Expressed in peripheral macrophages and intestinal myeloid-derived cells, is required for optimal PRR (pattern recognition receptor)-induced signaling, cytokine secretion, and bacterial clearance. Upon stimulation of a broad range of PRRs (pattern recognition receptor) such as NOD2 or TLR2, TLR3, TLR4, TLR5, TLR7 and TLR9, associates with YWHAQ/14-3-3T, which in turn leads to the recruitment and activation of MAP kinases and NF-kappa-B signaling complexes that amplifies PRR-induced downstream signals and cytokine secretion. In the intestine, regulates adherens junction stability by regulating the degradation of CYTH1 and CYTH2, probably acting as substrate cofactor for SCF E3 ubiquitin-protein ligase complexes. Stabilizes adherens junctions by limiting CYTH1-dependent ARF6 activation.
Synonyms: C1orf106; FLJ10901
Tractability: No criterion of Open Targets' tractability assessment is met for any kind of drug.
Gene: Protein-coding gene on chromosome 1 (200,891,003 to 200,915,742, forward strand). Ensembl gene ENSG00000163362.
Subcellular location: Nucleus; Cytoplasm
Subcellular location (Human Protein Atlas): Nucleoplasm; Nuclear bodies
Gene Ontology:
Molecular function: protein binding
Biological process: adherens junction maintenance; innate immune response; nucleotide-binding oligomerization domain containing 2 signaling pathway; pattern recognition receptor signaling pathway; positive regulation of canonical NF-kappaB signal transduction; positive regulation of cytokine production involved in immune response; positive regulation of interleukin-1 beta production; positive regulation of interleukin-10 production; positive regulation of interleukin-6 production; positive regulation of MAPK cascade; positive regulation of protein ubiquitination; positive regulation of stress-activated MAPK cascade; reactive oxygen species biosynthetic process; response to muramyl dipeptide; response to peptidoglycan; intestinal epithelial structure maintenance
Cellular component: cytoplasm; nuclear body; nucleoplasm; nucleus
Genetic constraint (gnomAD): Loss-of-function variants: 29 observed, 46.99 expected, observed/expected ratio (o/e) 0.62, 90% interval 0.46 to 0.84. The upper end of that interval is the gene's LOEUF score, 0.84, which puts it in group 3 of 6, group 1 being the genes least tolerant of losing a copy. Missense variants: 756 observed, 737 expected, observed/expected ratio (o/e) 1.03, 90% interval 0.97 to 1.09. Synonymous variants: 294 observed, 303.56 expected, observed/expected ratio (o/e) 0.97, 90% interval 0.88 to 1.07.
Homologues: Orthologues: chimpanzee INAVA (99% identical), macaque INAVA (97% identical), rat Inava (88% identical), mouse Inava (88% identical), guinea pig INAVA (86% identical), rabbit INAVA (83% identical), dog INAVA (80% identical), pig INAVA (76% identical), zebrafish inavab (38% identical), zebrafish inavaa (37% identical). Paralogues in human: CCDC120 (23% identical).
Diseases named in the same sentence as INAVA in open-access papers:
INAVA is named in the same sentence as 27 diseases in open-access papers, as found by Europe PMC text mining. Sharing a sentence is not in itself a finding about the gene and the disease. The quoted sentences say what the papers report.
Crohn disease (5 papers, 2014 to 2023). A gastrointestinal disorder characterized by chronic inflammation involving all layers of the intestinal wall, noncaseating granulomas affecting the intestinal wall and regional lymph nodes, and transmural fibrosis. "Innate immunity activator (INAVA, also named chromosome 1 open reading frame 106) is a protein coding gene known to be a risk locus for Crohn’s disease." (PMID 29632659, 2018).
inflammatory bowel disease (4 papers, 2022 to 2025). A spectrum of small and large bowel inflammatory diseases of unknown etiology. "Genome-wide association studies (GWAS) linked single nucleotide polymorphisms in the C1orf106 gene (also known as innate immunity activator INAVA) to increased risk of inflammatory bowel disease (IBD)." (PMID 39329715, 2024).
lung adenocarcinoma (3 papers, 2018 to 2025). A carcinoma that arises from the lung and is characterized by the presence of malignant glandular epithelial cells. "Innate immunity activator (INAVA) has been shown to be elevated in lung adenocarcinoma." (PMID 29632659, 2018).
ovarian carcinoma (1 paper, 2020). A malignant neoplasm originating from the surface ovarian epithelium. "In our study, several DEGs, including WFDC2, INAVA, and AOX1, in ovarian cancer revealed by our meta-analysis have been validated to potentially participate in ovarian cancer development and progression." (PMID 33135729, 2020).
INAVA also shares sentences with these, for which no sentence is quoted: breast carcinoma (5 papers); cancer (4); colitis (3); papillary thyroid cancer (2); psoriasis (2); tumor (2); celiac disease (1); cervical tumors (1); complication (1); deafness (1); diabetic nephropathy (1); diabetic retinopathy (1); epidermoid carcinoma (1); genetic disorders (1); gynecologic cancers (1); hepatocellular carcinoma (1); hypogonadism (1); invasive breast carcinoma (1); lung carcinoma (1); lymph node metastasis (1); Parkinson disease (1); thyroid cancer (1); ulcerative colitis (1).